AGR2 (anterior gradient 2, protein disulphide isomerase family member)
Diseases named in the same sentence as AGR2 in open-access papers (continued):
Sharing a sentence is not in itself a finding about the gene and the disease.
urothelial carcinoma (4 papers, 2015 to 2024). A malignant neoplasm derived from the transitional epithelium of the urinary tract (urinary bladder, ureter, urethra, or renal pelvis). "In urothelial carcinoma, AGR2 staining was unrelated to overall and recurrence‐free survival (p > 0.1)." (PMID 39533806, 2024). "Anteriorgradient 2 expression disappears in urothelial carcinoma (UC) and only 25% of primary tumors were observed to preserve AGR2 expression in a cohort of lymph node positive cases." (PMID 30544619, 2018). "AGR2 is secreted by the urothelial carcinoma cells as urinary AGR2 was measured in the voided urine of 25% of the cases analyzed in a cohort of cancer vs. non-cancer patients." (PMID 26894971, 2016). "Expression of AGR2 is lost in urothelial carcinoma, with only 25% of primary tumors observed to retain AGR2 expression in a cohort of lymph node-positive cases." (PMID 26894971, 2016). "In contrast, 5 cancer samples (25%) scored well above the PC3 reference value, a frequency that was expected given the percentage of primary urothelial carcinoma being positive for AGR2 as determined above." (PMID 26894971, 2016). "The fraction of AGR2-positive urine samples was consistent with the fraction of urothelial carcinoma that stained positive for AGR2." (PMID 26894971, 2016). "AGR2 expression is lost in urothelial carcinoma, but a minority of bladder tumors were found to retain AGR2." (PMID 26894971, 2016). "This suggested that urothelial carcinoma cells could secrete AGR2." (PMID 26894971, 2016). "Other potential diagnostic applications of AGR2 IHC may include the distinction of renal cell carcinomas (usually negative) from urothelial carcinomas (usually positive) from the kidney and mesotheliomas (usually negative) from adenocarcinomas (usually positive) of the lung." (PMID 39533806, 2024).
Barrett esophagus (3 papers, 2021 to 2025). Esophageal lesion lined with columnar metaplastic epithelium which is flat or villiform. "Moreover, the role of AGR2 in tumourigenesis in the oesophagus has previously been seen in higher gene expression of AGR2 in the OAC precursor condition Barrett’s oesophagus with respect to NAT, and increased expression of AGR2 in fibroblast cells was seen to promote tumour growth in mice." (PMID 40073002, 2025).
biliary tract cancer (3 papers, 2014 to 2024). "Although AGR2 expression was found to enhance tumor-associated phenotypes of the biliary tract cancer cells, caution should be taken to correlate these results with tumor progression and prognosis of biliary tract cancer patients directly." (PMID 25367337, 2014). "The knockdown of AGR2 in six biliary tract cancer cell lines using shRNA resulted in a decreased growth by 98% and an increase in the sensitivity of the cells to chemotherapeutic drugs." (PMID 31247903, 2019). "Loss of in vivo tumorigenic potential of SNU-478 cells after AGR2 knockdown suggests that AGR2 expression is required to establish and to maintain stable tumor xenograft of the biliary tract cancer cells." (PMID 25367337, 2014). "AGR2 is reported to be expressed in normal tissues of the biliary tract and the expression pattern is conserved in biliary tract cancer." (PMID 25367337, 2014). "An independent study on AGR2 expression in tissue specimens of biliary tract cancer patients revealed that AGR2 expression was higher in tumors of lower stage and advanced differentiation." (PMID 25367337, 2014). "Lack of correlation between in vitro tumor-promoting activity of AGR2 and pathologic findings in biliary tract cancer patients is an issue to be resolved." (PMID 25367337, 2014). "SNU-478 exhibited the highest level of AGR2 expression and the fastest growth among the six biliary tract cancer cells." (PMID 25367337, 2014). "It is conceivable that uncoupling of AGR2 expression from tumor progression of biliary tract cancers can be ascribed to peculiarity of biliary tract cancers including cancer microenvironment." (PMID 25367337, 2014). "AGR2 is thought to promote tumor formation by augmenting cell viability, anchorage-independent growth, and invasive properties of the biliary tract cancer cells." (PMID 25367337, 2014). "Since AGR2 manifested tumor promoting activity in ampulla of Vater cancer cells, pathologic relevance of AGR2 expression in carcinogenesis of the ampulla of Vater should also be investigated in detail." (PMID 25367337, 2014). "125I can inhibit the invasion of cholangiocarcinoma by suppressing AGR2 expression and modulating related pathways, although some studies have proposed that AGR2 has limited prognostic value for cholangiocarcinoma and that AGR2 expression decreases with biliary tract cancer progression." (PMID 39062458, 2024). "Thus, we examined the expression of AGR2 and its tumor-promoting activity in biliary tract cancer cells in this study." (PMID 25367337, 2014). "The expression of AGR2 was examined at the levels of mRNA and protein by real time RT-PCR and western blot analysis, respectively, in the six human biliary tract cancer cell lines that were established from adenocarcinomas of distinct differentiation status and anatomical locations." (PMID 25367337, 2014). "Thus, this study aimed to analyze the expression and functional role of AGR2 in development and maintenance of tumor phenotypes of biliary tract cancer cells." (PMID 25367337, 2014). "Thus, AGR2 expression is supposed to augment the tumorigenic potential of the biliary tract cancer cells by increasing the viability, invasiveness and anchorage-independent growth of these cells as was observed in other cancer cells." (PMID 25367337, 2014). "To this end, we determined AGR2 expression in six biliary tract cancer cell lines." (PMID 25367337, 2014). "An orthotopic biliary tract cancer model in which AGR2 expression can be modulated specifically in the biliary tract might be required to provide more definitive evidences on in vivo tumor-promoting function of AGR2 in biliary tract cancers." (PMID 25367337, 2014). "In a biliary tract cancer study on the SNU-245 and SNU-478 primary patient cell lines, low levels of AGR2 were correlated with increased disease-free survival (DFS), whereas high levels of AGR2 showed a lower DFS." (PMID 31247903, 2019).
biliary tract cancer (continued). "Despite that AGR2 is implicated in tumorigenesis and tumor progression of various cancers, AGR2 expression and its tumor-promoting role in biliary tract cancers have not yet been studied in detail." (PMID 25367337, 2014). "The AGR2 expression pattern in the biliary tract cancer cell lines did not appear to correlate with location or differentiation status of the original cancer tissue directly." (PMID 25367337, 2014). "However, the expression and tumor-promoting function of AGR2 in biliary tract cancer cells have not been investigated to date." (PMID 25367337, 2014). "However, the tumor promoting activity of AGR2 has not yet been determined in biliary tract cancers." (PMID 25367337, 2014).
colon adenocarcinoma (3 papers, 2022 to 2025). "The authors have shown that in a human colon adenocarcinoma cell line homo-dimerization of AGR2 occurs through intramolecular disulfide bond formation, and the dimeric form of AGR2 is capable of activating UPR signaling." (PMID 37175601, 2023).
Enteropathy (3 papers, 2021 to 2024). "A critical role of AGR2 in gastrointestinal health is also supported by the observation of a human enteropathy caused by a loss‐of‐function variant of AGR2 which is associated with a disturbed processing of mucins, increased ER stress, and goblet cell loss." (PMID 39533806, 2024). "These patients were found to have causative homozygous mutations in the gene AGR2; thus, their clinical syndrome was named “Enteropathy caused by AGR2 deficiency, Goblet cell loss, and ER stress”, or EAGLES syndrome." (PMID 36422736, 2023). "In summary, we describe a monogenic Enteropathy caused by AGR2 deficiency, Goblet cell Loss and ER Stress (EAGLES)." (PMID 34237462, 2021).
metastatic prostate carcinoma (3 papers, 2014 to 2022). A carcinoma that arises from the prostate gland and has spread to other anatomic sites. "AGR2 is elevated in patients with metastatic prostate cancer, pituitary adenomas." (PMID 35055132, 2022).
mucinous adenocarcinoma (3 papers, 2017 to 2022). An invasive adenocarcinoma composed of malignant glandular cells which contain intracytoplasmic mucin. "FOXM1 was demonstrated to be necessary and sufficient to cause the progression of lung adenomas into invasive mucinous adenocarcinomas in vivo by activating AGR2." (PMID 36304306, 2022).
asthma (2 papers, 2010 to 2020). "Notable hypermethylated probe-IDs with gene names included AGR2 (Anterior Gradient Protein 2), which plays a role in asthma and mucin production, and OTX2 (Orthodenticle Homeobox 2), which interacts with nitric oxide." (PMID 32850550, 2020). "An additional top hypermethylated gene is Anterior Gradient 2 (AGR2), a protein disulfide isomerase family member known to be involved in asthma and allergen-induced mucin production." (PMID 32850550, 2020). "The hypermethylated genes have roles in asthma (VGLL4, AGR2), neurologic development (AGAP1, OTX2), and immune regulation (SCAMP5, SLC11A1)." (PMID 32850550, 2020). "The present study adds to an accumulating body of evidence from gene-array studies that genes such as CLCA1, SerpineB2, MUC5AC, AGR2, CPA3, and tryptase are overexpressed in asthma, and suggests that these genes are more transcriptionally active in the EIB phenotype." (PMID 20052409, 2010).
cholangiocarcinoma (2 papers, 2019 to 2024). A carcinoma that arises from the intrahepatic biliary tree (intrahepatic cholangiocarcinoma) or from the junction, or adjacent to the junction, of the right and left hepatic ducts (hilar cholangiocarcinoma). "Conversely, AGR2 is overexpressed in cholangiocarcinoma, considered one of the most upregulated metastasis-related genes in highly metastatic cholangiocarcinoma." (PMID 39062458, 2024). "It is essential to carefully examine the correlation between AGR2 expression and clinicopathological data in a significant patient cohort, potentially positioning AGR2 as a novel therapeutic target in cholangiocarcinoma treatment." (PMID 39062458, 2024). "The oncogenic AGR2 isoform AGR2vH, generated by splicing, contributes to the metastatic phenotype of cholangiocarcinoma cells." (PMID 39062458, 2024). "In the realm of intrahepatic and extrahepatic cholangiocarcinoma, AGR2 immunotherapy is still in the exploratory phase." (PMID 39062458, 2024). "In another IHC study, staining showed that AGR2 expression was detected in one case of fibrolamellar carcinoma expressed in 14 cases of mucus-excreting intrahepatic cholangiocarcinomas." (PMID 31247903, 2019). "However, the evidence from these studies highlights the pro-invasive and metastatic role of AGR2 in cholangiocarcinoma." (PMID 39062458, 2024). "Similarly, gene expression analysis revealed a significant upregulation of AGR2 in the metastatic cholangiocarcinoma KKU-213L5 cell line." (PMID 31247903, 2019).
clear cell renal carcinoma (2 papers, 2022 to 2024). A malignant epithelial neoplasm of the kidney characterized by the presence of lipid-containing clear cells within a vascular network. "The strong link of high AGR2 with high grade and advanced stage in clear cell renal cell carcinoma (ccRCC) is in line with RNA data from the Cancer Genome Atlas (TCGA) which also suggested a poor prognosis in case of high AGR2 expression levels." (PMID 39533806, 2024). "High AGR2 expression was strongly linked to poor ISUP (p < 0.0001), Fuhrman (p < 0.0001), and Thoenes (p < 0.0001) grades as well as advanced pT stage (p = 0.0035) in clear cell renal cell carcinoma (ccRCC)." (PMID 39533806, 2024). "We identified five survival-related genes (AGR2, HAO2, IGF2BP1, MCCD1 and OLFM4) in clear cell renal carcinoma patients." (PMID 36516496, 2022).
ileocolitis (2 papers, 2018 to 2022). Ileocolitis or ileal Crohn's is the most common type of Crohn's disease. "Functional deficiency in the protein disulfide isomerase anterior gradient 2 (AGR2) has been linked with CD and leads to epithelial cell ER stress and ileocolitis in mice and humans." (PMID 36384110, 2022). "Increased ER stress associated with AGR2 correlated with the expansion of mucosal AIEC, which was sufficient to trigger ileocolitis in mono-associated Agr2-deficient mice." (PMID 36384110, 2022). "To determine the impact of the microbiome on the intestinal T cell activation associated with AGR2-dependent ileocolitis, we profiled ileal lamina propria CD4+ T cells in SPF Agr2−/− mice with ileocolitis." (PMID 36384110, 2022). "Here, to assess the interaction between AGR2 and CD dysbiosis, we analyzed AGR2-associated microbiome in human IBD and Agr2-deficient mice with ileocolitis." (PMID 36384110, 2022). "To determine the requirement for gut microbiota in the development of ileocolitis in Agr2−/− mice, we re-derived Agr2+/− and Agr2−/− mice under germ-free (GF) conditions and monitored them for 6 months." (PMID 36384110, 2022). "Although our results reveal the sufficiency of AIEC, but not other adherent commensals or non-invasive E. coli, to induce ER stress and ileocolitis in the absence of AGR2, we do not rule out the ability of additional pathobionts to induce disease." (PMID 36384110, 2022). "Here, we show the specificity of AIEC, but not non-pathogenic E. coli or other mucosal-associated commensals such as SFB, to induce epithelial ER stress and subsequent development of ileocolitis in the absence of AGR2." (PMID 36384110, 2022).
lung squamous cell carcinoma (2 papers, 2013 to 2023). "The AGR2 mRNA levels were negatively correlated with XBP1 protein levels in HCC (Spearman: − 0.169, p value: 0.02) in the TCGA, Pancancer microarray dataset and in lung squamous cell carcinoma (Spearman: − 0.16, p value: 3.65e-3)." (PMID 36899352, 2023). "Furthermore, a negative correlation between AGR2 and ATF6 was also reported in TCGA, lung squamous cell carcinoma (Spearman: − 0.104, p value: 0.02) and TCGA, pancreatic (Spearman: − 0.32, p value: 5.015e-3) cancer." (PMID 36899352, 2023).
mucinous tumors (2 papers, 2010 to 2021). "Therefore, AGR2 expression is often associated with mucinous tumours and their precursors, namely mucinous cystadenoma and mucinous borderline tumours, reaching 62 to 100% expression levels for mucinous tumours and 35–89% for endometrioid tumours." (PMID 34452625, 2021).
oral squamous cell carcinoma (2 papers, 2015 to 2022). "AGR2 expression was also shown to have a strong positive correlation with nanog homeobox (NANOG) in oral squamous cell carcinoma." (PMID 36482387, 2022).
ovarian tumors (2 papers, 2010 to 2021). "Since AGR2 has been reported to be associated with tumour progression and metastasis in several carcinomas, it would be interesting to decipher the role of AGR2 in ovarian tumour progression and metastasis." (PMID 34452625, 2021). "Moreover, eAGR2 blocking reduced the infiltration of vascular endothelial cells and fibroblasts in AGR2-positive ovarian tumours." (PMID 34452625, 2021). "Hence, cooperative or antagonistic biological effects could be expected, thus associating the differential expression of AGR2 and AGR3 to ovarian tumour outcomes." (PMID 34452625, 2021). "It has only been reported that AGR3 mediates cisplatin resistance in ovarian tumour xenograft, suggesting that AGR3 is pro-oncogenic and exerts functions independently of AGR2." (PMID 34452625, 2021). "We propose that AGR2 and AGR3 could exert different pro-oncogenic functions to confer specific and evolutive features to these ovarian tumours." (PMID 34452625, 2021). "In non-neoplastic ovarian epithelial tissue, immunoreactive (ir) AGR2 was not detectable, however, virtually all ovarian tumors of variable histotypes stain positively for irAGR2." (PMID 20525245, 2010). "All ovarian tumour types analysed exhibited elevated the median circulating levels of AGR2 (750 pg/mL vs. 200 pg/mL), and both serous and non-serous cases of all stages presented significantly increased the median circulating levels of AGR2 (875 pg/mL in serous tumours, vs. 680 pg/mL in non-serous)." (PMID 34452625, 2021).
papillary carcinomas of the thyroid (2 papers, 2014 to 2024). "Through a transcriptome microarray analysis, we have isolated Anterior gradient protein 2 (AGR2) as a gene up-regulated in papillary thyroid carcinoma (PTC)." (PMID 24976026, 2014). "We evaluated the expression level of AGR2 in the papillary thyroid cancer cell line TPC-1 in comparison to non-transformed thyroid cells Nthy-ori 3–1." (PMID 24976026, 2014). "While AGR2 expression was only weak or absent in the normal thyroid, it was moderate to strong in 46.0% of adenomas, 52.8% of follicular carcinomas, and 81.8% of papillary carcinomas of the thyroid." (PMID 39533806, 2024). "While AGR2 expression was weak or absent in our normal thyroid, a moderate to strong AGR2 staining was observed in 46% of adenomas, 52.8% of follicular carcinomas, 81.8% of papillary carcinomas, and 31.6% of anaplastic carcinomas of the thyroid." (PMID 39533806, 2024).
renal cell carcinoma (2 papers, 2022 to 2024). "That only few renal cell carcinomas were AGR2 positive also parallels our normal tissue findings as only few tubuli and collecting ducts had shown AGR2 staining in the normal kidney." (PMID 39533806, 2024). "In addition, AGR2 and IGF2BP1 promoted tumorigenesis by accelerating hypoxia state in renal cell carcinoma cell line." (PMID 36516496, 2022).
serous ovarian carcinoma (2 papers, 2015 to 2018). "Furthermore, AGR2 was associated with chemotherapy resistance in an analysis of survival in high-grade serous ovarian carcinoma." (PMID 30406031, 2018). "Instead, like high-grade serous ovarian cancer, higher cancer AGR2 expression is correlated with poorer survival." (PMID 26445321, 2015).
small cell carcinoma (2 papers, 2016 to 2021). A neuroendocrine carcinoma composed of small malignant cells which are often said to resemble "oat cells" under the microscope. "In the small cell carcinoma section, liver cells adjacent to the tumor mass were moderately stained for AGR2 expression whereas the tumor cells were completely unstained (note that AGR2 in normal cells such as bladder urothelial cells is not secreted)." (PMID 27283903, 2016). "Immunostaining of adenocarcinoma (in a bone metastasis) and small cell carcinoma (in a liver metastasis) obtained from autopsies showed the difference in AGR2 expression between these two cancer types." (PMID 27283903, 2016). "The control were tissue digestion media containing no AGR2 prepared from benign prostate 10-076 NP and small cell carcinoma LuCaP 145.1 xenograft." (PMID 27283903, 2016). "Although we cannot definitively rule out other molecules present in the PCD-inducing tissue digestion media but absent in media of benign prostate and a small cell carcinoma xenograft, AGR2 is a common high abundance molecule among these sources." (PMID 27283903, 2016).
ulcerative colitis (2 papers, 2012 to 2024). An inflammatory bowel disease involving the mucosal surface of the large intestine and rectum. "In summary, two total SNPs in the 5′ promoter region of the AGR2 gene were found to be associated with the risk haplotype of ulcerative colitis in two independent populations, providing further evidence for a role for AGR2 in disease pathogenesis." (PMID 23245351, 2012). "A cohort of 2,540 patients having either ulcerative colitis or Chron’s disease was investigated for SNPs in AGR2 and AGR3; in total, 30 SNPs were identified, 25 were located in the AGR2 gene, while 5 were located in the AGR3 gene." (PMID 23245351, 2012).